IL1B (interleukin 1 beta)
Diseases named in the same sentence as IL1B in open-access papers (continued):
Sharing a sentence is not in itself a finding about the gene and the disease.
infection (continued). "Specifically, fever‐induced HSP70/90 drives macrophage adaptation, T‐cell migration, and Th17 differentiation, whereas IL‐1β/IL‐6/TNF‐α enhances lymphocyte adhesion, Th1‐polarized and leukocyte exhibits promising clinical potential in oncology and infection control." (PMID 41298282, 2026). "Activation of FcγRs in the absence of infection typically promotes inflammatory responses via cytokines like IL-1β and TNF-α." (PMID 41485094, 2026). "Indeed, the abundance of Enterobacteriaceae or Escherichia-Shigella was positively correlated with rectal temperature at 12 and 24 h post-infection, serum TNF-α level, and jejunal IL-1β, IL-10, and TNF-α mRNA levels." (PMID 41547922, 2026). "Analysis of differentially expressed genes in the LC group compared with the CC group at day 90–180 after infection identified an increase of multiple proinflammatory markers, such as IL6, NLRP3, TNF, JAK2, CSF2, IL1B and IL10, in the LC compared with the CC group." (PMID 41388153, 2026). "The predominance of caspase-8 (without releasing IL-1β and IL-18) reshapes inflammatory responses and cell death mechanisms during infection." (PMID 41208996, 2025). "Thus, we evaluated serum cytokine levels, such as IL-1β, IL-6, IL-10, MCP-1, and IFN-γ in EV-A71 infected PLG-KO and WT mice at 2, 4, and 6 days post-infection." (PMID 40377310, 2025). "Unlike the ‘cell-free’ infection conditions in which we previously observed an increase in IL-1β levels 4h post-infection, we did not detect measurable differences in IL-1β secretion at this early timepoint following the establishment of SUPT1:MDM coculture." (PMID 39229127, 2025). "Secreted IL-1β, CCL4, IFN-α and IFN-γ were increased by Th17 priming of BECs prior to infection." (PMID 41332562, 2025). "However, at 24 h post-infection, the expression levels of TNF-α, IL-1β, and IL-6 were markedly reduced, while the secretion of the chemokine IL-8 continued to increase, and the anti-inflammatory cytokine IL-10 was significantly upregulated (P < 0.05)." (PMID 40874199, 2025). "TNF-α and IL-1β activate the canonical NF-κB pathway in endothelial cells (ECs), thereby stimulating the production of cell adhesion molecules, such as E-selectin and ICAM-1, which facilitate neutrophil transmigration to sites of infection or injury." (PMID 40562870, 2025). "Interleukin-1 beta (IL-1β), interleukin-6 (IL-6), and serum amyloid A (SAA) are well-known pro-inflammatory cascades, exhibiting high expression levels in rainbow trout (Oncorhynchus mykiss) during Ich infections." (PMID 40509043, 2025). "Thus, cytokines such as IL-1β, IL-6, IL-8, and IFN-α play fundamental roles in orchestrating the immune system’s multifaceted response to injury, infection, and malignancy." (PMID 40284869, 2025). "Conversely, the percentage of IL-1β+ and TNF+ microglia increased by day 6 post-infection." (PMID 40771825, 2025). "As further confirmation, infection of NLRP3-deleted THP-1 cells and BMDMs completely prevented IL-1β secretion, while preserving secretion of the inflammasome-independent cytokine TNFα, highlighting the specificity of the effect for inflammasome-dependent responses." (PMID 40747430, 2025). "Although IL-1β levels in total tissue lysate were low, this was not surprising at 2 and 5 weeks post-infection." (PMID 41196042, 2025). "In addition, in vitro studies using a human blood-brain barrier (BBB) model showed that USUV infection leads to upregulation and release of inflammatory cytokines such as IL-6, TNF-α, and IL-1β, both on the apical and basolateral sides of the barrier." (PMID 40731345, 2025). "The results regarding the levels of cytokines studied in this work (IL-1β, IL-6, TNF-α) may suggest that the presence of intracellular C. trachomatis in the infection will play a dominant role in the immune system response." (PMID 40647668, 2025).
infection (continued). "Although the precise mechanisms underlying CHIKV-induced AIN remain incompletely understood, existing evidence implicates an excessive inflammatory response, particularly the upregulation of pro-inflammatory cytokines such as IL-1β, IL-6 and TNF-α during the acute phase of infection." (PMID 40766840, 2025). "Other studies have shown a reduction in caspase‐1 activation and IL‐1β secretion in bone‐marrow‐derived macrophage (BMDMs) lacking NLRP6 compared to WT BMDMs following infection with Staphylococcus aureus or L. monocytogenes." (PMID 39351983, 2025). "infection did not change the levels of cytokines interleukin 1β (IL-1β), IL-6, IL-10, interferon gamma (IFN-γ), and tumor necrosis factor alpha (TNF-α)." (PMID 40302747, 2025). "Compared with Mtb‐infected control macrophages, the level of IL1β was significantly reduced in both HIF1‐KD and GBP1‐KD cells after infection with HN878 or CDC1551, while TNFα and IL6 were significantly reduced only in HN878‐infected HIF1‐KD and GBP1‐KD macrophages." (PMID 41287823, 2025). "Importantly, infection of iMGs from both iPSC lines (iMG #1 and iMG #2) with Lai/YU-2env resulted in an MOI-dependent increase in p24Gag secretion and IL-1β secretion at day 3 pi, which was suppressed upon EFV treatment." (PMID 40920844, 2025). "Moreover, PEGylated phages effectively suppressed infection-driven cytokines, reducing IL-6, TNF-α, IFN-γ, and IL-1β levels toward baseline while inducing weaker IgG responses." (PMID 41309396, 2025). "Studies indicate that while primary human airway epithelial (HAE) cells possess functional inflammasomes supporting SARS-CoV-2 replication, they do not serve as the primary source of IL-1β secretion during infection." (PMID 40072090, 2025). "Additionally, quantification of the levels of IL-1β, IL-6, and TNF-α pro-inflammatory cytokines showed that old murine BMMs displayed similar levels of IL-1β, IL-6, and TNF-α 24 h after infection with Aa or Pg compared with controls in young BMMs." (PMID 40649955, 2025). "Following intrastromal infection with USA300, we found that neutrophils comprise >90% of the cellular infiltrate in corneas during early infection, and that disease severity and bacterial killing were dependent on neutrophil production of IL-1β." (PMID 41415470, 2025). "Consistent with the severe airway inflammation observed via histopathology analysis, sublethal infection with wild-type K7 boosted the secretion of the inflammatory cytokines TNF-α, IL-6 and IL-1β, whereas the levels of these cytokines were significantly reduced by IFA treatment." (PMID 39761301, 2025). "The activation of NF-κB in macrophages initiates an inflammatory cascade and promotes their recruitment to sites of infection, where activated M1 macrophages secrete TNF-α, IL-1β, IL-6, and other cytokines to mobilize neutrophils and initiate the host response." (PMID 41347221, 2025). "Research indicates that approximately half of patients with community-acquired acute hepatitis C can spontaneously clear the virus, and significantly higher levels of IL-1β, IL-1RA, IL-6, IFN-γ, and FGF-2 were detected in the serum of patients achieving self-limited infection." (PMID 40934209, 2025). "Priming with TNFα led to slightly enhanced infection levels and IL-1β secretion in the absence of Vpx-VLPs." (PMID 40920844, 2025). "UPEC infection led to a statistically significant increase in IL1B transcription in the non-proliferating cell population, whereas infection significantly increased transcription of S100A14, a member of the S100 protein family, in all cell clusters." (PMID 40766562, 2025). "Additionally, PRV-GXLB-2013 infection induced a highly significant upregulation in mRNA expressions of TNF-α, IL-1β, IL-6, NF-κB p65, RIP3, and MLKL (p < 0.01), alongside a pronounced downregulation of IκBα (p < 0.01), in both brain tissues and C8-D1A cells." (PMID 40732040, 2025).
infection (continued). "The combination of IL-1β, IL-8 and IL-6 showed high AUC values, indicating a high predictive accuracy to identify febrile UTI, which would be of interest to localize infection to the urinary tract when diagnosing a child with fever of unknown origin." (PMID 40856487, 2025). "At 24 hours post-infection (hpi), western blot analysis revealed marked upregulation of NLRP3 together with increased expression of pro-IL-1β in CEK cells, which was accompanied by enhanced secretion of mature IL-1β into the culture supernatant." (PMID 41334910, 2025). "Circulating levels of TNF-α, IL-1β, and IL-17a were elevated in mice infected with fas2Δ/Δ at 24 h post-infection compared to WT, whereas IFN-γ and IL-6 levels were significantly decreased but comparable to the saline (mock infection) control." (PMID 40138332, 2025). "Polarized M1 THP-1 macrophages were resistant to TcpC’s influence on IL-1β but not TNFα or IL-6 secretion during an infection with CFT073." (PMID 41310197, 2025). "However, at 48 hpi, IL-1β and IFN-γ expression levels were significantly higher following infection with AG234 than the NC." (PMID 40426284, 2025). "P. aeruginosa isolates from PwCF failed to induce inflammasome activation, IL-1β release and pyroptotic cell death in primary macrophages isolated during both stable infection and exacerbation." (PMID 40791588, 2025). "When we differentiated THP-1 cells to M0 macrophages using Phorbol 12-myristate 13-acetate (PMA) we failed to observe a TcpC-mediated further increase of IL-1β secretion during an infection with CFT073." (PMID 41310197, 2025). "Since a mitochondrial hyperactive phenotype describes a compensatory mechanism to meet the energy demand of an infection or immune response, we investigated whether AGS-induced mitochondrial ATP synthesis supports HIV replication and IL-1β release in AMs." (PMID 41463390, 2025). "Both defense mechanisms become problematic as NETs and IL-1β are present at elevated levels in CF airways, potentially creating a destructive cycle that exacerbates lung damage rather than protects against infections." (PMID 40791588, 2025). "While neither IL-1β nor LDH release was detected in cell culture supernatants at 30 min post-infection, IL-1β and LDH levels steadily increased in all samples with longer infection times and to varying degrees." (PMID 39688411, 2025). "Additionally, in vitro studies have shown that the infection activates the NLRP3 inflammasome, producing IL-1β and IL-18, and induces the cleavage of caspase-1 and cell death." (PMID 40943382, 2025). "Furthermore, XY018 treatment reduced inflammatory cell infiltration and decreased viral mRNA levels, as well as TNF-α, IL-1β, and IL-6 mRNA levels in the lung tissues of H5N1 virus-infected mice on day 3 after infection." (PMID 41134862, 2025). "The frequencies of latently infected cells were generally lower compared to productive infection, and in most cases, not significantly altered by IL1B treatment." (PMID 40442100, 2025). "The lack of IL-1β and IL-8 response in our CHSE-214 infected cells is probably caused by the decreased infection levels in the presence of Aq." (PMID 40244309, 2025). "Notably, myeloid cells in AG ferrets showed significantly elevated expression of inflammatory cytokines, including IL-1β, IL-10, IL-18, NFκB1, and S100A8, as well as upregulated IFNGR2 expression throughout infection, especially 4dpi." (PMID 40794649, 2025). "Western blot results demonstrated that in IBV-infected CEK cells, baicalin significantly promoted the protein expression of IL-1β, IL-6, TNF-α, TLR7, and MyD88 at 24 h post-infection (hpi), whereas it markedly suppressed the expression of these factors at 48 hpi." (PMID 41375455, 2025). "Similarly, at 12h post-infection, FH-treated cells showed decreased mRNA levels of IL-6 [~ -1.2 log10], IFN-α [~ -1.9 log10]), IL-1β [~ -2.7 log10], and IFN-α [~ -2.9 log10], RANTES [~ -0.8 log10], and IL-8 [~ -2.1 log10] compared to untreated cells." (PMID 40895576, 2025).
infection (continued). "IL-1β was significantly higher 24 h post-infection, but the difference was small, and 48 h post-infection concentrations were no different from uninfected conditions." (PMID 40586572, 2025). "Together, these data demonstrate that under infection conditions in which Mtb alone minimally induced inflammasome assembly, Mtb-specific mAbs complexed to Mtb potently stimulate NLRP3-dependent inflammasome activation and IL-1β secretion." (PMID 40747430, 2025). "The expression of IL-1β, IFN-α2, IFN-γ, TNF-α, MCP-1 (CCL2), IL-6, IL-8 (CXCL8), IL-10, IL-12p70, IL-17A, IL-18, IL-23, and IL-33 was assessed in apical washes at different time points after infection using a 13-plex immunoassay." (PMID 40143308, 2025). "IL-1β is a potent pro-inflammatory cytokine, and the IL-1 signaling pathway can lead to fever and the production of other pro-inflammatory cytokines and chemokines, which can help in controlling SARS-CoV-2 by recruiting immune cells to the site of infection." (PMID 40742121, 2025). "In acute and chronic infection, IL-1β levels were greatest in the small intestine, although infection did not significantly impact IL-1β abundance at the time points sampled." (PMID 41196042, 2025). "The results demonstrated that the levels of pStat3and pNF-κB p65 were significantly upregulated after ME49 infection, and downregulated after depletion of BFD2 Simultaneously, qRT-PCR was used to quantify Il1b, Ifng, and Cd86 transcripts in cells infected with T. gondii." (PMID 40906736, 2025). "Notably, inflammasome scores (based on IL1B, IL18, NLRP3, GSDMD, PYCARD) remained stable in YG CMs and IMs during infection but increased consistently in AG subsets from 4 to 6 dpi." (PMID 40794649, 2025). "In human monocyte cell lines (THP‐1), the maturation of pro‐IL‐1β was decreased at early time points following infection with MYXV however, there was no cleavage of caspase‐1 at these time points." (PMID 39878363, 2025). "Of the many proteins reported to be elevated early on in COVID-19 infection and that we tested, only CD14 delineated individuals with Cov from nLongC, while IL-1β decreased over time in Cov but not nLongC many months to years post infection." (PMID 41369364, 2025). "In the present study, we established a cohabitat infection model of ichthyophthiriasis in darkbarbel catfish, cloned the complete coding sequences (CDS) of IL-1β, IL-6, and SAA, and dynamically monitored their transcription levels by RT-qPCR throughout the infection period." (PMID 40509043, 2025). "To investigate whether RBMX2 mediates intracellular inflammation by regulating the tightness of the epithelial barrier, we measured the mRNA levels of inflammatory factors (IL-1β, TNF, and IL-6) in RBMX2 knockout EBL cells post-infection." (PMID 41277807, 2025). "Although infection with two invasive NTHi strains did not cause noticeable differences in ICAM-1 or TNF-α expression, NTHi 08-252 induced higher IL-1β release." (PMID 40137696, 2025). "In addition, 25–100 mg/kg baicalin reduced the mRNA expression levels of IL-1β, IL-6, IL-8, IL-18, TNF-α, and COX-2 in the spleen compared to the infection group (p < 0.05)." (PMID 40427533, 2025). "The robust disproportionality signals observed for the SOC “infections and infestations” (ROR: 1.37, 95% CI = 1.13–1.65) directly stem from the dual role of IL-1β in orchestrating both innate immune defense against pathogens and regulation of autoinflammatory cascades." (PMID 41471316, 2025). "Furthermore, we found distinct cytokine profiles among groups, especially the marked increase of TNF-α and IL-10 in infection-induced ALI and IL-1β in gastric aspiration." (PMID 39969856, 2025).
infection (continued). "IL-1α and IL-1β were not detectable in the uninfected A-431 cells; induction occurred only by C. albicans, with no relevant differences when comparing mono and dual infection." (PMID 40284741, 2025). "The RNA of Il6 and Ptgs2 detected by qPCR show similar trends to the transcriptome data, although the RNA of Tnfa and Il1b showed constant elevation post infection, which was not completely consistent with the transcriptome data." (PMID 38992966, 2025). "Supplementation with Vpx-VLPs not only enhanced infection by over 100-fold, but was also sufficient to trigger IL-1β secretion even in the absence of TNFα." (PMID 40920844, 2025). "RT-qPCR analysis at 12 hours post-infection indicated that NVP treatment strongly suppressed virus-induced transcription of pro-inflammatory cytokines Il6, Tnfα, and Il1β compared to the DMSO controls, approaching baseline expression levels in RAW264.7 cells across all viral challenges." (PMID 40948770, 2025). "However, ΔeseB-D, ΔeseB, ΔeseC, and ΔeseD were unable to induce host cell death, IL-1β release, Casp1 activation, or GSDMD cleavage following infection." (PMID 39951384, 2025). "We found that both il1b and fosl1a can be significantly induced in tirap+/+embryos upon LPS infection, while no different expression was found in tirap-/- embryos compared to mock injection control." (PMID 39781449, 2025). "Studies have shown that if the infection is not completely cleared from the body, it can lead to the continuous production of pro-inflammatory cytokines such as IL-1β, IL-6, IL-8, and TNF-α, which can limit the formation of granulation tissue and microvessels." (PMID 40529353, 2025). "The upregulation of IL1B upon infection was absent in male mice, while the IL6 levels were higher relative to those in uninfected male mice, although significantly lower compared to those in the infected female group." (PMID 40143355, 2025). "Furthermore, the IL-1β, IL-18, and LDH levels in bronchoalveolar lavage fluid (BALF) from WT mice increased in a dose-dependent manner 7 days after MPXV infection." (PMID 41225161, 2025). "IL-1β can also act on epithelial cells to produce antimicrobial peptides, such as DEFB4/HBD2, and promotes endothelial cell expression of adhesion molecules, facilitating the recruitment of other immune cells to sites of infection." (PMID 40076802, 2025). "Moreover, the immune-related genes IL-1β and TNF-α were significantly upregulated in supplemented groups, both before and after infection, suggesting enhanced immune readiness and responsiveness." (PMID 41188425, 2025). "Infection with A. veronii triggered immune responses in mice that were mediated by TNF-α and IL-1β." (PMID 39980697, 2025). "In response to infection with Listeria monocytogenes, Salmonella enterica serovar Typhimurium (S. Typhimurium) or Escherichia coli, WT mice and mice lacking NLRP6 have similar levels of caspase‐1 activation and IL‐1β release." (PMID 39351983, 2025). "During both infections, macrophages and monocytes are the primary sources of TNF-α and IL-1β." (PMID 40420159, 2025). "The results showed that, during PRV (MOI = 0.4) infection, compared to the empty vector group, all METTL3 groups (METTL3, METTL3-S43A, METTL3-S50A, and METTL3-S525A) significantly enhanced the mRNA transcription levels of IL-1β, IL-8, IL-6 and TNF-α." (PMID 40802811, 2025). "Protein levels of CCL4, IL-1β, and TNF-α correlated with expression of the interferon signaling module in BECs with increased protein levels after RV-16 infection correlating with increased expression post-infection." (PMID 41332562, 2025). "Under mechanical injury, stress, or infection, the AF and NP secrete TNF-α and IL-1β." (PMID 40356987, 2025). "Our work establishes IL-1β and IFN-I as key cytokines shaping the severity of the infection." (PMID 40100932, 2025).